RNU6-799P (RNA, U6 small nuclear 799, pseudogene)
Gene: Small nuclear RNA gene on chromosome 17 (15,311,345 to 15,311,451, forward strand). Ensembl gene ENSG00000200437.
Homologues: Orthologues: chimpanzee U6 (99% identical), macaque U6 (91% identical). Paralogues in human: RNU6-1158P (91% identical), RNU6-38P (91% identical), RNU6-1011P (90% identical), RNU6-29P (90% identical), RNU6-17P (89% identical), RNU6-18P (89% identical), RNU6-25P (89% identical), RNU6-338P (89% identical), RNU6-33P (89% identical), RNU6-1 (88% identical), RNU6-12P (88% identical), RNU6-13P (88% identical), and 1289 more.